NUDT17 (nudix hydrolase 17)
Description:
Acts as a decapping enzyme capable of hydrolyzing monomethylated capped RNAs (in vitro). Hydrolyzes monomethylated capped RNA after alpha and beta phosphates to form N(7)-methyl-GDP. Shows low activity towards unmethylated capped RNA.
Synonyms: FLJ34433
Tractability: No criterion of Open Targets' tractability assessment is met for any kind of drug.
Gene: Protein-coding gene on chromosome 1 (145,845,603 to 145,848,954, forward strand). Ensembl gene ENSG00000186364.
Subcellular location (Human Protein Atlas): Nucleoplasm
Gene Ontology:
Molecular function: 5'-(N(7)-methylguanosine 5'-triphospho)-[mRNA] hydrolase activity; NADH pyrophosphatase activity
Biological process: NAD+ catabolic process; NADP+ catabolic process; RNA decapping
Cellular component: peroxisome
Genetic constraint (gnomAD): Loss-of-function variants: 37 observed, 35.43 expected, observed/expected ratio (o/e) 1.04, 90% interval 0.8 to 1.37. The upper end of that interval is the gene's LOEUF score, 1.37, which puts it in group 5 of 6, group 1 being the genes least tolerant of losing a copy. Missense variants: 459 observed, 384.91 expected, observed/expected ratio (o/e) 1.19, 90% interval 1.1 to 1.29. Synonymous variants: 192 observed, 161.66 expected, observed/expected ratio (o/e) 1.19, 90% interval 1.05 to 1.34.
Homologues: Orthologues: chimpanzee NUDT17 (97% identical), dog NUDT17 (75% identical), pig NUDT17 (75% identical), mouse Nudt17 (65% identical), rat Nudt17 (64% identical), zebrafish nudt17 (40% identical). Paralogues in human: NUDT18 (18% identical), NUDT12 (13% identical), NUDT1 (9% identical).
Diseases named in the same sentence as NUDT17 in open-access papers:
NUDT17 is named in the same sentence as 6 diseases in open-access papers, as found by Europe PMC text mining. Sharing a sentence is not in itself a finding about the gene and the disease. The quoted sentences say what the papers report.
breast carcinoma (1 paper, 2026). "While variants in the NUDT17 gene have been associated with cancer biology, their involvement in breast cancer is still inadequately investigated, especially within South Asian populations." (PMID 41855232, 2026). "This study investigated the association between two NUDT17 polymorphisms, rs9286836 and rs2004659, and breast cancer risk in Bangladeshi women using a case-control design." (PMID 41855232, 2026). "Expression analysis further demonstrated elevated NUDT17 levels in breast cancer tissues and genotype-dependent expression effects for both variants." (PMID 41855232, 2026).
gout (1 paper, 2022). A condition characterized by painful swelling of the joints, which is caused by deposition of urate crystals. "Three LD blocks existed in chromosome 1 for the variants relating to gout, which were composed of genes DNAJC16, AGMAT (first block), PDZK1, CD160, NUDT17 (second block), TRIM46, MUC1, MTX1, and ASH1L (third block)." (PMID 36221101, 2022). "Surprisingly, variants on chromosome 1, such as rs7546668 (DNAJC16), rs10927807 (AGMAT), rs9286836 (NUDT17), rs4971100 (TRIM46), rs4072037 (MUC1), and rs2974935 (MTX1), showed significant associations with gout in both discovery and replication cohorts (all p-values < 1e−8)." (PMID 36221101, 2022). "Moreover, rs9286836 (NUDT17) and rs4971100 (TRIM46), rs4072037 (MUC1) and rs2974935 (MTX1) also revealed significant associations with gout (all p-values <1e−8)." (PMID 36221101, 2022). "This study performed a GWAS in a large sample size and found genes DNAJC16, AGMAT, NUDT17, TRIM46 MUC1, and MTX1 on chromosome 1 relating to gout disease." (PMID 36221101, 2022). "Surprisingly, variants on chromosome 1 located in genes DNAJC16, AGMAT, NUDT17, TRIM46, MUC1 and MTX1 showed significant associations with gout, which finding had not been reported before." (PMID 36221101, 2022).
liver cancer (1 paper, 2023). An epithelial or non-epithelial malignant neoplasm that arises from the liver. "We then elucidated the nature of the observed NUDT17 dependency in liver cancer cell lines." (PMID 38134284, 2023). "Hence, we propose the existence of a unique vulnerability of liver cancer cells harboring a chr8p-deleted background due to their NUDT17 dependency." (PMID 38134284, 2023). "Furthermore, using a whole-genome CRISPR-Cas9 screening approach, we identified the Nudix (nucleoside diphosphate–linked moiety X) hydrolases NUDT17 and NUDT18 as synthetic lethal paralogs, suggesting that NUDT17 may be targetable in liver cancer cells with chr8pLOH." (PMID 38134284, 2023).
cancer (2 papers, 2023 to 2026). A tumor composed of atypical neoplastic, often pleomorphic cells that invade other tissues. "S6, A to F), confirming NUDT17 dependency in the three chr8p-deleted cancer cells HLF, HLE, and HCC68." (PMID 38134284, 2023). "In an organ continuously exposed to toxic agents, such as the liver, targeting ROS response is a promising strategy, as NUDT17 addiction is specific to chr8p-deleted cancer cells." (PMID 38134284, 2023).
retinopathy (1 paper, 2024). "In GWAS analysis, we found 12 SNPs had a significant association (p < 10-4) with HCQ retinopathy in genes LCE4A, HRNR, OR2T4, NUDT17, CCDC66, PRSS3, PABPC1 and IGHV." (PMID 38548946, 2024).
tumor (1 paper, 2023). "This confirmed that the NUDT17 dependency in chr8p-deleted tumor cells is caused by reduced NUDT18 expression." (PMID 38134284, 2023). "We showed that the NUDT17 is a candidate target allowing to selectively inhibit chr8p-deleted tumor cells." (PMID 38134284, 2023). "Using this target identification strategy, we found that chr8p deletion sensitizes tumor cells to targeting of the reactive oxygen sanitizing enzyme NUDT17." (PMID 38134284, 2023). "In conclusion, we propose that NUDT18 reduction by chr8pLOH sensitizes these tumor cells for NUDT17 targeting." (PMID 38134284, 2023). "The development of NUDT17 specific inhibitors will allow for specific targeting of tumor cells with chr8p deletion without affecting normal cells." (PMID 38134284, 2023). "We performed in-depth validation of our CRISPR-Cas9 screen in independent isogenic cell clones of three different cell lines that clearly validated that lack of the NUDT18 paralog in chr8pLOH tumor cells sensitized them to NUDT17 ablation." (PMID 38134284, 2023). "In addition, NUDT17 was up-regulated in HCC tumor tissue compared to surrounding nontumor tissue and high NUDT17 expression correlated with decreased patient survival." (PMID 38134284, 2023).